ENSG00000258989 (novel protein)
Gene: Protein-coding gene on chromosome 14 (61,529,128 to 61,657,964, forward strand). Ensembl gene ENSG00000258989.
Genetic constraint (gnomAD): Loss-of-function variants: 4 observed, 12.35 expected, observed/expected ratio (o/e) 0.32, 90% interval 0.16 to 0.74. Missense variants: 103 observed, 152.31 expected, observed/expected ratio (o/e) 0.68, 90% interval 0.58 to 0.8. Synonymous variants: 51 observed, 54.16 expected, observed/expected ratio (o/e) 0.94, 90% interval 0.75 to 1.19.